FUT8 (fucosyltransferase 8)
Diseases named in the same sentence as FUT8 in open-access papers (continued):
Sharing a sentence is not in itself a finding about the gene and the disease.
lung adenocarcinoma (7 papers, 2017 to 2025). A carcinoma that arises from the lung and is characterized by the presence of malignant glandular epithelial cells. "Sections stained with IHC for FUT8 in normal lung tissue, lung adenocarcinoma, and lung squamous cell carcinoma were retrieved and downloaded from the HPA database." (PMID 40373023, 2025). "In a coculture analysis using human lung adenocarcinoma A549 cells and antibody-secreting B cells, the downregulation of the FUT8 (α1,6 fucosyltransferase) gene and a low level of core fucose of the N-glycan in IgG in antibody-secreting B cells were observed after coculture." (PMID 37865317, 2023). "CircASPH (Aspartate Beta-Hydroxylase) expression is upregulated in lung adenocarcinoma and, finally, circFUT8 (Fucosyltransferase 8) functions as a tumor suppressor in bladder cancer cells where low circFUT8 was associated with poor prognosis, high histological grade, and lymph node metastasis." (PMID 33920880, 2021). "In addition, we found that FUT2 and FUT8 were overexpressed in lung adenocarcinoma." (PMID 29228607, 2017).
schizophrenia (7 papers, 2020 to 2025). A major psychotic disorder characterized by abnormalities in the perception or expression of reality. "In a study focused on FUT8-knockout in mice that monitored their behavior and neurological activity, the results in FUT8-deficient mice indicated the presence of a schizophrenia-like phenotype, which manifested as a decrease in social interaction or enhanced locomotor activity." (PMID 37240090, 2023). "Models that fail to express core fucosylation (FUT8-knock out) show an impairment in hippocampal long-term potentiation, presenting a schizophrenia-like behavior and phenotype." (PMID 38178977, 2024). "Fut8 homozygous KO (Fut8−/−) mice exhibit a schizophrenia-like phenotype with a decrease in working memory and long-term potentiation." (PMID 38042483, 2023). "Our previous studies demonstrated that Fut8 homozygous knockout (KO) (Fut8−/−) mice exhibit memory impairments and abnormal behaviors consistent with schizophrenia-like phenotypes, along with decreased hippocampal long-term potentiation (LTP) compared to the wild-type (Fut8+/+) mice." (PMID 39864626, 2025).
colon carcinoma (6 papers, 2017 to 2025). "Our model suggests that the dysregulated fucosylation of aging epithelial cells, caused by the imbalance of FUT2 and FUT8 expression, increases the risk of colon cancer in older adults." (PMID 38456503, 2024). "FUT8 is a crucial gene that causes colon cancer and is linked to tumour immunity." (PMID 40729369, 2025). "Our study revealed a noteworthy increase in FUT8 expression in colon tumors, particularly among older adults." (PMID 38456503, 2024). "Intriguingly, the tumor-promoting FUT2 and FUT8 expression was highly expressed in tumor colon cE02, cE03, and cE06 epithelial subsets in aging colon tumor." (PMID 38456503, 2024). "Interestingly, the expression of FUT8 exhibited a significant increase in colon tumor samples cE01, cE02, cE03, and cE06 as a result of the aging process." (PMID 38456503, 2024). "In colon cancer, FUT8 was found to be a therapy target by mediating lysosomal proteolysis." (PMID 38182713, 2024).
osteosarcoma (6 papers, 2021 to 2025). A usually aggressive malignant bone-forming mesenchymal neoplasm, predominantly affecting adolescents and young adults. "While fucosyltransferases such as FUT8 are generally implicated in promoting tumor progression through core fucosylation of N-glycans, recent findings suggest a more complex and possibly inverse role in osteosarcoma." (PMID 40864783, 2025). "In particular, a recent relevant study demonstrated that FUT8 downregulation in osteosarcoma cells enhanced metastasis via upregulation of L1CAM, indicating a potential tumor-suppressive function in this context." (PMID 40864783, 2025). "This implies that a diminished expression of FUT8 plays a role in the growth and progression of osteosarcoma." (PMID 38534381, 2024). "While FUT8 is generally overexpressed in most cancers, it exhibits a unique downregulation in osteosarcoma relative to normal tissues." (PMID 38256141, 2024). "FUT8 is expressed at reduced levels in osteosarcoma patients and in human osteosarcoma cell lines such as MNNG/HOS, U2OS, and 143B." (PMID 38534381, 2024). "However, FUT8 was found to be expressed at lower levels in osteosarcoma, leading to lower core fucosylation levels of TNF receptors." (PMID 36611197, 2023). "Hence, it can be deduced that FUT8 plays a tumor suppressor role, and its induction may then represent a novel therapeutic strategy in osteosarcoma." (PMID 38534381, 2024). "However, the function of FUT8 in the progress of osteosarcoma (OS) has not been reported." (PMID 34857735, 2021).
thyroid papillary carcinomas (6 papers, 2010 to 2021). "High expression of Fut8 was observed in 33.3% of papillary carcinomas and the incidence was directly linked to tumor size and lymph node metastasis." (PMID 20652009, 2010). "Furthermore, higher expression of FUT8 was also found to be associated with larger tumor size and lymph node metastasis in papillary thyroid carcinoma." (PMID 34703796, 2021). "Furthermore, decreases in Fut8 expression in papillary carcinomas might be linked to anaplastic transformation." (PMID 20652009, 2010). "In papillary thyroid carcinoma, high expression of FUT8 is related to an increased tumour volume and lymph node metastasis." (PMID 34093814, 2021). "The expression of FUT8 in normal follicles is very low, but FUT8 is highly expressed in 33.3% of papillary carcinomas, which is directly related to tumour size and lymph node metastasis." (PMID 34093814, 2021). "Thyroid papillary carcinoma, which maintains a relatively glandular structure, highly expresses FUT8; however, anaplastic transformation reduces its expression." (PMID 32099910, 2020). "Further studies are needed to elucidate the link between FUT8 and aggressive papillary carcinomas, identify the mechanisms involved, and understand whether FUT8 plays a role in the development of papillary carcinoma prior to anaplastic transformation." (PMID 33466384, 2021). "Notably, the increase in Fut8 expression and activity was observed in thyroid papillary carcinomas and correlated to tumour size and lymph node metastasis, and thus Fut8 expression represents a biomarker of progression of thyroid papillary carcinomas." (PMID 24689054, 2014). "Positive staining of Fut8 was observed in papillary carcinomas." (PMID 20652009, 2010). "We concluded that expression of Fut8 might be a key factor for the progression of thyroid papillary carcinomas, but not of follicular carcinomas." (PMID 20652009, 2010).
glioma (5 papers, 2015 to 2025). A benign or malignant brain and spinal cord tumor that arises from glial cells (astrocytes, oligodendrocytes, ependymal cells). "For glioma, upregulated FUT8 expression was associated with shorter OS in female patients (RR= 1.99, 95% CI: 1.15-3.44)." (PMID 33323540, 2020). "The majority of such studies (n=5: NSCLC, BC, DLBCL, GC, glioma) found significant correlations of FUT8 expression with OS of tumor, and also associations between survival and clinicopathological features, particularly tumor stage." (PMID 33323540, 2020). "FUT8 expression levels in the other 4 tumor types (glioma, DLBCL, GC, BC) were also correlated with OS." (PMID 33323540, 2020). "Ras activation additionally led to increased expression of FUT8, which agrees with a previous report showing strong LCA-lectin binding in tissue glioma cells, whereas the LCA binds to sugar chains containing core fucose." (PMID 26132161, 2015).
triple-negative breast carcinoma (5 papers, 2021 to 2025). An invasive breast carcinoma which is negative for expression of estrogen receptor (ER), progesterone receptor (PR), and human epidermal growth factor receptor 2 (HER2). "The FUT8 catalyzed core fucosylation of N-glycans, and knockdown of FUT8 rescued the immunosuppressive function in triple negative breast cancer cells, whereas upregulation of FUT8 was identified as features of metastatic melanoma." (PMID 37798282, 2023). "Taken together, these data indicate that fucosyltransferase FUT8 mediates aberrant N-glycosylation of B7H3 and suppresses the immune response in triple-negative breast cancer." (PMID 33976130, 2021). "Here the authors show that FUT8 mediates fucosylation of B7H3 to limit the immune response to triple-negative breast cancer as a potentially targeted mechanism of non-responsiveness to current checkpoint therapies." (PMID 33976130, 2021). "Overexpression of FUT8 can suppress the immune response in triple-negative breast cancer by mediating the abnormal N-glycosylation of B7H3, which may account for the lack of response to anti-PD1/PDL1 immunotherapy in triple-negative breast cancer patients." (PMID 36611197, 2023).
lymph node metastasis (4 papers, 2019 to 2022). "After accounting for the effects of age, sex, differentiation, tumor status, stage and lymph node metastasis, multivariate Cox regression analysis indicated that the level of FUT8 expression was an independent predictor of poor OS (HR = 2.87; 95% CI = 1.42–5.77; p = .003)." (PMID 35237113, 2022).
pulmonary fibrosis (4 papers, 2021 to 2023). Chronic progressive interstitial lung disorder characterized by the replacement of the lung tissue by connective tissue, leading to progressive dyspnea, respiratory failure, or right heart failure. "FUT8 upregulation is observed in a bleomycin-induced pulmonary fibrosis rat model, while glycyrrhizic acid can alleviate IPF by inhibiting FUT8-mediated core fucosylation of TGF-βR and WNT." (PMID 37256139, 2023). "Together, these results confirmed that cellular senescence existed and FUT8 enzyme activity was overexpression in BLM-induced lung fibrosis." (PMID 37724903, 2023). "Furthermore, FUT8 regulates pericyte activation through multiple signaling pathways, transforms pericytes into myofibroblasts, and promotes pulmonary fibrosis." (PMID 37196106, 2023). "Our previous study demonstrated that core fucosylation modification, catalyzed by a specific core fucosyltransferase (FUT8) can regulate the activation of multiple signaling pathways, and inhibiting CF can alleviate pulmonary fibrosis in mice induced by bleomycin." (PMID 34329195, 2021). "Inhibition of cellular senescence by eliminating the FUT8 gene could attenuate pulmonary fibrosis." (PMID 37724903, 2023). "Moreover, our data also suggested, for the first time, using alveolar epithelial cell-specific FUT8 conditional knockout (CKO) mouse models, however, inhibition of cellular senescence by eliminating the FUT8 gene could attenuate pulmonary fibrosis in vivo." (PMID 37724903, 2023). "Notably, using alveolar epithelial cell-specific FUT8 conditional knockout mouse models, however, inhibition of cellular senescence by deleting the FUT8 gene could attenuate pulmonary fibrosis in vivo." (PMID 37724903, 2023).
thyroid cancer (4 papers, 2010 to 2025). "One of the few studies examining the role of FUT8 in thyroid cancer utilized immunohistochemistry of 133 thyroid tumours, and found FUT8 is associated with larger tumour volumes and lymph node metastasis." (PMID 33466384, 2021). "As a result of immunohistochemical studies, involving 133 cases of thyroid cancer, the expression of Fut8 was found to be quite low in normal follicles." (PMID 20652009, 2010). "When we established a monoclonal antibody for Fut8, we performed the first immunohistochemical study on thyroid cancer." (PMID 20652009, 2010). "However, a prior study suggested that FUT8 was overexpressed in thyroid cancer, and changes in core fucosylation of glycans were documented." (PMID 39766189, 2024).
endometriosis (3 papers, 2019 to 2024). The growth of functional endometrial tissue in anatomic sites outside the uterine body. "The sole difference in expression between endometriosis stages was observed for two genes related to the invasion, migration, and metastasis pathway (FUT8 and SPRY2 genes), which showed higher gene expression levels in patients with stages III/IV." (PMID 38069001, 2023). "FUT8 has not previously been studied in endometriosis tissue samples but has been implicated in the epithelial–mesenchymal transition and metastasis." (PMID 38069001, 2023). "Compared to those with I/II endometriosis, increased mean gene expression in endometriotic tissue from women with III/IV endometriosis was observed for MMP7 (0.10 vs. 0.00), FUT8 (1.14 vs. 0.02), and SOX2 (1.51 vs. 0.36)." (PMID 38674005, 2024).
invasive ductal carcinoma (3 papers, 2017 to 2024). "Inhibition of FUT8 by 2FF in human invasive ductal carcinoma reduced E-selectin ligand expression, cell proliferation, and ERK1/2 and p38 MAPK activation." (PMID 38253527, 2024). "Our mining data reveal a trend toward elevated FUT8 expression at mRNA levels in distal metastatic tumors compared to primary breast tumors or in invasive ductal carcinoma (IDC) compared to non-invasive ductal carcinoma in situ (DCIS)." (PMID 28982386, 2017).
metastatic tumor (3 papers, 2017 to 2025). "Taken together, our data suggest FUT8 is upregulated at both the gene and protein level in high grade prostate tumours and in patients with metastatic disease." (PMID 40387385, 2025). "The present study documented the higher mRNA levels of FUT4, FUT5, and FUT8 in advanced stage and metastatic tumor which highlights their role as valuable indicators of aggressiveness and metastatic potential of the disease." (PMID 34703796, 2021).
myeloma (3 papers, 2007 to 2017). "This property is related to the lower expression of the Fut8 gene in rat myeloma YB2/0 cells compared with other commonly used cell lines, such as CHO cells." (PMID 28427157, 2017). "It appears that the rat myeloma cell line YB2/0 has a mean copy number of fut8 gene of 2.8 ± 1.4 whereas the rat primary lymphocyte has only 2.3 ± 0.8 of the same gene and the negative control with the NRP shows no hybridization." (PMID 21208406, 2011). "Our preliminary experiments have also indicated that the tandem siRNA expression vector designed for the double knockdown of mouse FUT8 and GMD also worked in mouse myeloma cell lines NS0 and SP2/0." (PMID 18047682, 2007).
ovarian carcinoma (3 papers, 2022 to 2025). A malignant neoplasm originating from the surface ovarian epithelium. "In ovarian cancer, FUT8 activates the hyper core fucosylation of copper transporter 1 to suppress cisplatin uptake into OC cells." (PMID 36611197, 2023). "FUT8 expression is increased in ovarian cancer and the down-regulation of FUT8 significantly inhibits the invasion and spread of tumor cells." (PMID 36499043, 2022).
cervical cancer (2 papers, 2021 to 2024). A primary or metastatic malignant neoplasm involving the cervix. "Metabolites from lactic acid bacteria in the vaginal environment can activate FUT8′s transcription and enhance core fucosylation in mucosal epithelial cells, thereby inhibiting the proliferation and invasion of cervical cancer cells." (PMID 38256141, 2024). "Knocking out FUT8 was found to promote the proliferation and invasion of cervical cancer cells, while the abundance of lactic acid bacteria positively correlated with the core fucosylation modification level." (PMID 38256141, 2024). "Core fucosyltransferase gene (Fut8) knockout promoted the proliferation and migration of cervical cancer cells." (PMID 34799549, 2021). "The proliferation and migration of cervical cancer cells was significantly enhanced after the Fut8 gene was knocked out, while reintroduced of the Fut8 gene reversed the effects." (PMID 34799549, 2021). "In addition, the tumor weight and volume were significantly greater in the 0Fut8−/− SiHa cell-injected nude mice when compared with those injected with Fut8+/+ SiHa cells, revealing that the core fucosylation has a protective effect against cervical cancer development." (PMID 34799549, 2021).
chronic obstructive pulmonary disease (2 papers, 2020 to 2023). A chronic and progressive lung disorder characterized by the loss of elasticity of the bronchial tree and the air sacs, destruction of the air sacs wall, thickening of the bronchial wall, and mucous accumulation in the bronchial tree. "However, FUT8 polymorphisms have been associated with the levels of high-density lipoprotein cholesterol (rs10483776), hypertension, and chronic obstructive pulmonary disease, which are common comorbidities in PTSD." (PMID 36982780, 2023). "In addition, a decrease in Fut8 activity is observed in cigarette smoke-exposed mice, which is related to the development of chronic obstructive pulmonary disease (COPD)." (PMID 32900381, 2020).
COVID-19 (2 papers, 2022 to 2024). A disease caused by infection with severe acute respiratory syndrome coronavirus 2. "In our study, rs7146742 in the intron of FUT8 was identified to be associated with NAbs level of COVID-19 vaccine immunization." (PMID 36451823, 2022).
E. coli infection (2 papers, 2022 to 2024). "In order to verify that the FUT8 signaling pathway plays a role in E. coli infection with IPEC-J2 cells, we used RT-qPCR to detect the expression levels of key genes in the signaling pathway." (PMID 36499043, 2022). "This suggests that the expression of the FUT8 gene is closely related to the collective resistance of E. coli infection, and FUT8 may be involved in the life process of E. coli F18 resistance regulation." (PMID 36499043, 2022). "Therefore, it is speculated that FUT8 acts in a critical role in the process of E. coli infection; furthermore, the low expression of FUT8 is conducive to the enhancement of E. coli resistance in piglets." (PMID 36499043, 2022). "Therefore, we speculate that the down-regulation of FUT8 expression may help pigs to resist E. coli infection, pathogen adhesion, and pathogen colonization through a series of signaling and immune regulations." (PMID 36499043, 2022). "Interestingly, we also observed increased FUT8 expression induced by other enveloped viral infections, including VSV, HSV-1 and SARS-CoV-2 infection, but not by SeV or E. coli infection." (PMID 38253527, 2024).
endometrial cancer (2 papers, 2020 to 2025). Primary or metastatic malignant neoplasm involving the endometrium (mucous membrane that lines the endometrial cavity). "•Silencing of fucosyltransferase 8 suppressed the proliferation of Ishikawa cells, an endometrial cancer cell line." (PMID 32099910, 2020). "Therefore, we aimed to identify the expression of FUT8 in endometrial endometrioid carcinoma and investigate the effect of the partial silencing of the FUT8 gene on the cell proliferation of Ishikawa cells, an epithelial-like endometrial cancer cell line." (PMID 32099910, 2020). "Indeed, a partial knockdown of FUT8 significantly suppressed the proliferation of Ishikawa cells, which was an epithelial-like endometrial cancer cell line, indicating a crucial role of FUT8 in their proliferation." (PMID 32099910, 2020).